ACE (angiotensin I converting enzyme)
Diseases named in the same sentence as ACE in open-access papers (continued):
Sharing a sentence is not in itself a finding about the gene and the disease.
mitral valve disease (2 papers, 2020 to 2021). "Twenty‐one dogs with mitral valve disease that were genotyped for the ACE gene polymorphism." (PMID 32112596, 2020). "The efficacy of ACE-inhibitors in delaying disease progression and prolonging survival in dogs with both preclinical and clinical mitral valve disease is debated because published study results are contradictory." (PMID 34256860, 2021).
morbid obesity (2 papers, 2024). An excess of body weight, normally defined as an individual with a body mass index greater than 35 or a body weight greater than one hundred percent of ideal body weight. "Given the strong relationship between cytokine protein levels and ACE, a multiple linear regression model was conducted to identify the main predictors of hepatic ACE levels in patients with morbid obesity and MASLD." (PMID 39337863, 2024). "The multiple linear regression model results reveal a significant relationship between hepatic levels of ACE and the cytokines IL-4 and IL-13 in patients with morbid obesity and MASLD." (PMID 39337863, 2024).
muscular dystrophies (2 papers, 2020 to 2021). "Despite multiple possible mechanisms of muscular dystrophy, regular heart examination and the preventive prescription of angiotensin-converting enzyme (ACE) inhibitors, as well as early initiation of the therapy have been shown to be effective." (PMID 33516230, 2021). "In a study conducted by Kajimoto and coworkers, patients with different types of muscular dystrophies were assigned to receive either an ACE inhibitor plus a beta-blocker (carvedilol) for at least 2 years or an ACE inhibitor alone (cilazapril or enalapril) for at least 3 years." (PMID 32075145, 2020).
Nasal congestion (2 papers, 2010 to 2022). Reduced ability to pass air through the nasal cavity often leading to mouth breathing. "Medications such as alpha and beta-blockers, centrally acting anti-hypertensives, and angiotensin converting enzyme (ACE) inhibitors that inhibit sympathetic tone lead to vasodilation and symptoms of nasal congestion." (PMID 20465792, 2010).
Nasal polyps (2 papers, 2011 to 2021). "In bronchial biopsy, ever-smoking and ever-history of nasal polyps were significantly associated with ACE levels on univariate regression, but both became non-significant on multivariate analysis." (PMID 33413387, 2021).
Neurogenic bladder (2 papers, 2020 to 2023). A type of bladder dysfunction caused by neurologic damage. "The analysis of serum ACE, ACE 2 and urinary ACE were not significant in patients with myelomeningocele and neurogenic bladder with renal injury previously detected by renal DMSA." (PMID 32648420, 2020).
ovarian serous cystadenocarcinoma (2 papers, 2021 to 2023). A malignant serous cystic epithelial neoplasm arising from the ovary. "The distinctive expression profiles of ACE within ovarian serous cystadenocarcinoma (OV) and kidney renal clear cell carcinoma (KIRC) demonstrated a discernible association with ubiquitin modification, facilitated by E3 ligases." (PMID 37812215, 2023). "Differential expression patterns of ACE in ovarian serous cystadenocarcinoma (OV) and kidney renal clear cell carcinoma (KIRC) were correlated with ubiquitin modification involving E3 ligases." (PMID 34671200, 2021).
pancreatic diseases (2 papers, 2023). "Finally, the underlying comorbidities found in obese individuals such as heart, kidney, and pancreatic diseases may also be associated with the dysregulation of the ACE/ACE2 axis in these disease-related tissues." (PMID 37443562, 2023).
pemphigus (2 papers, 2011 to 2014). Pemphigus is a group of rare autoimmune diseases that cause blistering of the skin and mucous membranes (mouth, nose, throat, eyes, and genitals).This conditioncan occur at any age, but often strikes people in middle or older age. "These associations could be further confirmed in SIDER dataset, where ACE inhibitors were significantly enriched in drugs listing pemphigus (p = 5.7E-10) and β-blockers were associated with cold extremities (p = 4.5E-6)." (PMID 22205936, 2011). "pemphigus is reported to be induced by angiotensin-converting enzyme (ACE) inhibitors, and cold extremities is antihypertensives especially by β-adrenergic blockers." (PMID 22205936, 2011). "In our prediction results, we also found that ACE inhibitors are significant enriched in the drugs predicted as pemphigus positive (Fisher's exact p = 1.4E-3); whereas β-adrenergic blockers have significantly higher frequency in drugs predicted as cold extremities positive (p = 0.02)." (PMID 22205936, 2011).
postmenopausal osteoporosis (2 papers, 2017 to 2022). Metabolic disorder associated with fractures of the femoral neck, vertebrae, and distal forearm. "ACE and AGTR1 were shown to be highly expressed in the femoral head in an ovariectomized rat model of postmenopausal osteoporosis." (PMID 35445013, 2022).
renal artery obstruction (2 papers, 2024 to 2025). Narrowing or occlusion of the renal artery or arteries. "Renal artery obstruction increased SBP and DBP, intrarenal ACE activity, Ang II levels, Na+ retention, and αENaC expression in both kidneys." (PMID 40362413, 2025).
Right ventricular hypertrophy (2 papers, 2014 to 2021). In this case the right ventricle is more muscular than normal, causing a characteristic boot-shaped (coeur-en-sabot) appearance as seen on anterior- posterior chest x-rays. "For instance, one study showed that the ACE D/D genotype is associated with less right ventricular hypertrophy, whereas another reported a correlation between the ACE D/D genotype and the severity of symptoms." (PMID 34441050, 2021).
Seizure (2 papers, 2020 to 2021). A seizure is an intermittent abnormality of nervous system physiology characterized by a transient occurrence of signs and/or symptoms due to abnormal excessive or synchronous neuronal activity in the brain. "Seizures were observed in both untreated (a high BP control) SHRs and in SHRs treated with AT1R antagonist and ACE inhibitor." (PMID 33424536, 2020).
squamous cell carcinoma (2 papers, 2022 to 2023). A carcinoma arising from squamous epithelial cells. "Three (13.6%) of the patients with squamous cell carcinoma had pre-medication with ACE inhibitors, 3 (13.6%) had pre-medication with HCT, and 2 (9.1%) of the patients were taking both drugs." (PMID 35175408, 2022). "This study shows that 36.4% of patients with histologically proven basal cell carcinoma and 36.4% of patients with squamous cell carcinoma have pre-medication with HCT and/or ACE inhibitors." (PMID 35175408, 2022).
ulcer disease (2 papers, 2008 to 2023). A lesion on the surface of the skin or a mucous surface, produced by the sloughing of inflammatory necrotic tissue. "Another interpretation of our results is the "treatment-risk paradox" in which the history of cancer or ulcer disease inhibits the use of ACE inhibitors, perhaps due to concerns of polypharmacy or intolerance of the medication due to the underlying disease." (PMID 19061507, 2008). "A report by Iakubov and Usmanova indicated that prophylactic use of ACE inhibitors reduced indomethacin-induced ulcers and erosions of the stomach in humans." (PMID 19061507, 2008). "It is possible that ACE inhibitors protect against the development of cancer or ulcer disease, although confirmation of these hypotheses must await additional investigation." (PMID 19061507, 2008).
Ureteral obstruction (2 papers, 2019 to 2022). Obstruction of the flow of urine through the ureter. "Exogenous Klotho expression suppressed the upregulation of AGT, renin, ACE, and AT1R protein expression and normalized blood pressure in 5/6 nephrectomised rats and unilateral ureteral obstruction (UUO) mice." (PMID 36059935, 2022).
abscess (1 paper, 2025). An inflammatory process characterized by the accumulation of pus within a newly formed tissue cavity which is the result of a bacterial, fungal, or parasitic infection or the presence of a foreign body. "However, significantly lower richness were found for feces than skin (Chao1 p = 1.68 × 10−3, ACE p = 2.24 × 10−3, two-tailed paired t-test) and abscess (Chao1 p = 1.75 × 10−3, ACE p = 4.15 × 10−4)." (PMID 39866571, 2025).
Acute bronchitis (1 paper, 2013). Inflammation of the large airways of the lung with rapid onset and short course usually associated with cough, mucus production, shortness of breath, wheezing, and chest tightness. "Time-dependent analysis with adjusted hazard ratios (HR) for all-cause mortality according to calcium channel blocker, ACE inhibitor or angiotensin receptor blocker, or statin use in subgroups of patients with a diagnosis of acute bronchitis." (PMID 23840599, 2013).
adrenocortical carcinoma (1 paper, 2022). "The mutations of NOS3 and ACE have prognostic potential for the overall survival of adrenocortical carcinoma and skin cutaneous melanoma patients, respectively." (PMID 35513851, 2022).
agranulocytosis (1 paper, 2020). "GWAS of agranulocytosis induced by antithyroid drugs or sulfasalazine, cough induced by angiotensin-converting enzyme (ACE) inhibitors, narcolepsy induced by Pandemrix and atypical femoral fractures induced by bisphosphonates have been published." (PMID 31949290, 2020).
alcoholic cardiomyopathy (1 paper, 2012). A dilated cardiomyopathy which is associated with consumption of large amounts of alcohol over a period of years. "In this regard, gene polymorphism for angiotensin converting enzyme (ACE) is associated with increased vulnerability to alcoholic cardiomyopathy." (PMID 21977024, 2012).
anterior wall myocardial infarction (1 paper, 2012). "In addition, the ACE DD genotype is also associated with greater ACS severity, including more stenosed vessels, greater occlusion of the left anterior descending branch, and a greater risk of anterior wall myocardial infarction and also of sudden cardiac death." (PMID 22333273, 2012).
aortic atherosclerosis (1 paper, 2024). A atherosclerosis that involves the aorta. "Further, ApoE KO animals transplanted with ACE 10/10 bone marrow had a 35% reduction of aortic atherosclerosis as compared to mice transplanted with WT bone marrow." (PMID 38763333, 2024). "In the PCSK9 model, the ACE 10/10 mice had a 44% reduction of aortic atherosclerosis compared to WT mice." (PMID 38763333, 2024).
aortic valve calcification (1 paper, 2009). "Moreover, in a recent retrospective study by O'Brien and co-workers, the use of ACE inhibitors was associated with slower progression of aortic valve calcification." (PMID 19257900, 2009).
aplastic anemia (1 paper, 2018). Anemia resulting from bone marrow failure (aplastic or hypoplastic bone marrow). "Due to no improvement in clinical symptoms and an increase in aplastic anemia, it is unpractical to choose an addition of NEP inhibitors (ecadotril) to standard therapies including angiotensin-converting enzyme (ACE) inhibitors." (PMID 29344085, 2018).
aristolochic acid nephropathy (1 paper, 2023). "Here, we investigated whether mice with reduced renal angiotensin I-converting enzyme (ACE−/−) are protected against aristolochic acid nephropathy (AAN)." (PMID 36520238, 2023).
artery occlusion (1 paper, 2020). "More recently, ACE inhibitor therapy in mice was established to abolish the release of spleen-derived monocytes into the circulation, resulting in lower inflammatory cell infiltration to the infarct territory after coronary artery occlusion." (PMID 32125488, 2020).
Arthralgia (1 paper, 2019). "We further made analysis between ACE I/D polymorphism and some clinical features of OA and found DD genotype of this SNP was associated with arthralgia." (PMID 30765613, 2019). "Furthermore, we investigated the association between ACE I/D polymorphism and clinical features of OA and found DD genotype of this SNP was associated with arthralgia." (PMID 30765613, 2019).
B-cell lymphoma (1 paper, 2025). "Compared with HCs group, B-cell lymphoma patients showed significantly lower ACE and Chao1 index of intestinal flora (P<0.05)." (PMID 41357232, 2025).
basal cell carcinoma (1 paper, 2022). A carcinoma involving the basal cells. "Forty-three (21.7%) of the patients with basal cell carcinoma, had pre-medication with ACE inhibitors, 17 (8.6%) had pre-medication with HCT, and 12 (6.1%) of the patients were taking both drugs." (PMID 35175408, 2022). "In our study, 22.7% of the patients with registered basal cell carcinomas took ACE inhibitors." (PMID 35175408, 2022).
Bicuspid aortic valve (1 paper, 2024). The presence of an aortic valve with two instead of the normal three cusps (flaps). "However, despite the wide availability of these medications, there is presently no proof to support the beneficial role of beta-blockers, ACE inhibitors, or ARBs in aortopathies linked to bicuspid aortic valve (BAV)." (PMID 39452287, 2024).
C3 glomerulopathy (1 paper, 2025). "Likewise, patients with complement-mediated kidney disease, such as C3 glomerulopathy, are often treated with angiotensin-converting enzyme (ACE) inhibitors or angiotensin receptor blockers, which markedly increase renin levels." (PMID 40242769, 2025).
Cardiac sarcoma (1 paper, 2021). "Cardiac sarcoma patients might profit from administration of beta-adrenergic blockers, ACE inhibitors, QT-prolonging antiarrhythmic drugs, antibiotics, and antipsychotics." (PMID 34359782, 2021).
cerebral aneurysm (1 paper, 2021). "In a study comparing patients with unruptured or ruptured cerebral aneurysm to controls, a significant drop in the mRNA expressions of ACE and AT1 has been observed." (PMID 34201646, 2021). "The authors therefore excluded any implication of AT1 or ACE in cerebral aneurysm formation, as further supported by the lack of effect of an ARB treatment." (PMID 34201646, 2021).
cerebral microbleeds (1 paper, 2023). Cerebral microbleeds are a group of pathological processes affecting the small arteries, arterioles, capillaries and venules of the brain, as detected by brain imaging techniques. "Comparison of the longitudinal changes in the number of cerebral microbleeds according to the angiotensin-converting enzyme (ACE) gene insertion (I)/deletion (D) polymorphism." (PMID 37900609, 2023). "However, no previous study has evaluated the relationship between the ACE I/D polymorphism and cerebral microbleed (CMB), an important CSVD marker." (PMID 37900609, 2023).
cerebral small vessel disease (1 paper, 2023). Cerebral small vessel disease is the term currently used to pathological processes that affect the brain parenchymal circulation (arterioles, capillaries, and veins). "The angiotensin-converting enzyme (ACE) insertion (I)/deletion (D) polymorphism has been studied as a genetic candidate for cerebral small vessel disease (CSVD)." (PMID 37900609, 2023).
cheilitis (1 paper, 2025). An inflammatory process affecting the lip. "Additionally, after using medications such as ACE inhibitors, local anesthetics, aspirin, and others, cheilitis, an inflammation of the lips that manifests as redness, burning, and fissures, may develop (Lugović‐Mihić 2018)." (PMID 39370676, 2025).
cholangiocarcinoma (1 paper, 2022). A carcinoma that arises from the intrahepatic biliary tree (intrahepatic cholangiocarcinoma) or from the junction, or adjacent to the junction, of the right and left hepatic ducts (hilar cholangiocarcinoma). "ACE and ACE-related signaling are active specifically as elements driving cholangiocarcinoma growth." (PMID 35626167, 2022).
chronic GVHD (1 paper, 2015). "In the univariate analysis, ACE-27 (p = 0.004), graft source (p = 0.05), primary disease (p = 0.01) and type of conditioning regimen (p <0.001) were associated with chronic GVHD." (PMID 26394228, 2015).
chronic rhinosinusitis (1 paper, 2021). Chronic form of sinusitis. "In contrast, the specimens from the eosinophilic chronic rhinosinusitis group generally showed less ACE immunoreactivity in the epithelial layer." (PMID 33928889, 2021).
cicatricial alopecia (1 paper, 2023). Scarring hair loss, also known as cicatricial alopecia, is the loss of hair which is accompanied with scarring. "A few cases of non-cicatricial alopecia induced by ACE inhibitors have been identified." (PMID 37763773, 2023).
colorectal adenoma (1 paper, 2014). An adenoma that arises from the colon or rectum. "In a human trial, long-term use of an ACE inhibitor also reduced the incidence and size of colorectal adenomas." (PMID 24959250, 2014).
congenital hypothyroidism (1 paper, 2025). A thyroid hormone deficiency present from birth. "This is marked by decreased fetal renal REN expression, temporally decreased fetal pulmonary and renal ACE levels, and decreased postnatal ANGII concentrations following congenital hypothyroidism." (PMID 40939099, 2025).
congenital muscular dystrophy (1 paper, 2014). A muscular dystrophy that is characterized by diminished muscle tone (hypotonia), progressive muscle weakness and degeneration (atrophy), abnormally fixed joints, spinal rigidity, and delays in reaching motor milestones such as sitting or standing unassisted. "Interestingly, it was shown that the RAS is activated in various muscular dystrophies such as DMD or congenital muscular dystrophy (CMD) and that dystrophic muscle in humans has increased levels of ACE, which may explain the elevated CTGF levels, but this remains to be proved." (PMID 24877152, 2014).
conjunctivitis (1 paper, 2019). Inflammation of the conjunctiva of the eye. "Also, similar to diazoxide, Ketotifen, used to reduce conjunctivitis allergic effects, can also interact with the ACE." (PMID 31249365, 2019).
cortical atrophy (1 paper, 2022). "Specifically, increased angiotensin-converting enzyme (ACE) levels have been found in the patients with greater progression of deep WMH volume but less progression of cortical atrophy, suggesting a complex role of ACE in the brain." (PMID 36119691, 2022).
Crigler-Najjar syndrome (1 paper, 2023). Crigler-Najjar syndrome (CNS) is a hereditary disorder of bilirubin metabolism characterized by unconjugated hyperbilirubinemia due to a hepatic deficit of bilirubin glucuronosyltransferase (GT) activity. "Analysis of the local conformation of ACE in plasma of patients with Gilbert and Crigler-Najjar syndromes allowed us to speculate that binding of mAbs 1G12 and 6A12 to plasma ACE could be a natural sensor for estimation of free bilirubin level in plasma." (PMID 36831070, 2023).
dacryoadenitis (1 paper, 2025). Inflammation and enlargement of the lacrimal gland. "Of the 14 patients diagnosed with dacryoadenitis, ACE was positive in 2 of 13 (15.3%) patients tested, lysozyme in 1 of 12 (8.3%) patients tested, SS-A in 1 of 5 (20%) patients tested, and C-ANCA 1 of 10 (10%) patients tested." (PMID 40475267, 2025).
Dent disease (1 paper, 2020). Dent disease is a rare genetic renal tubular disease characterized by manifestations of proximal tubule dysfunction. "In addition, ACE inhibitors/ARBs are well tolerated, and they are partially efficient in controlling albuminuria in Dent disease." (PMID 32495484, 2020). "The aim of the present study was to characterize the phenotypic spectrum and assess the antialbuminuric response to ACE inhibitor and/or ARB therapy in a Chinese cohort of children with Dent disease." (PMID 32495484, 2020).
diaphragmatic hernia (1 paper, 2020). A congenital or acquired weakness or opening in the diaphragm which allows abdominal contents to protrude into the chest cavity; congenital diaphragmatic hernias are caused when the embryonic diaphragm fails to fuse. "For example, polymorphisms in the gene encoding angiotensin-converting enzyme (ACE) have been associated with IPAH and with diaphragmatic hernia with persistent pulmonary hypertension." (PMID 33256119, 2020).